PLG (plasminogen)
Diseases named in the same sentence as PLG in open-access papers (continued):
Sharing a sentence is not in itself a finding about the gene and the disease.
tumor (continued). "The massive body of research indicates that activating the plasminogen system is crucial for the invasion of tumor cells." (PMID 39754146, 2025). "Studies have shown that PLAUR can promote tumor metastasis by mediating plasminogen activation and extracellular matrix degradation." (PMID 40474968, 2025). "The most highly expressed gene on this list was PLG (plasmin heavy chain A), which had a 28-fold increase in expression in liver metastasis compared to the primary tumour." (PMID 40241172, 2025). "uPAR promotes metastatic spread by localizing plasminogen activation at the tumor–stroma interface, enabling ECM degradation and intravasation." (PMID 41154366, 2025). "Several lines of evidence have shown that tumor-derived EVs and exosomes serve as sophisticated delivery vehicles for multiple components of the plasminogen activation system." (PMID 41463352, 2025). "There is growing evidence that components of the plasminogen-plasma system are involved in tumor growth, invasion, and metastasis by modulating cell migration and angiogenesis." (PMID 40396123, 2025). "Plasminogen reduction resulted in significantly reduced primary tumor growth for multiple lines in both subcutaneous and orthotopic models." (PMID 37971174, 2024). "Among many proteases that support tumor survival, plasminogen is one of the most common proteolytic enzymes in the body." (PMID 39001286, 2024). "Elimination of plasminogen from the PDAC TME resulted in changes in the accumulation of tumor‐supporting cells and tumor cell survival." (PMID 37971174, 2024). "The reduction in the number of micro‐metastatic lesions in as short as 3 h after injection in Plg− mice suggested that the loss of plasminogen conferred a reduction in the initial adhesion and/or survival of KPC tumor cells within the lung." (PMID 37971174, 2024). "Genetic or pharmacological depletion of plasminogen was found to suppress primary PDAC tumor growth and metastatic potential." (PMID 37971174, 2024). "STAT3 regulates PLG expression, promoting a thrombotic state that facilitates tumor cell migration and invasion in ccRCC." (PMID 39348357, 2024). "The serine protease inhibitor clade E member 1 (SERPINE1) is a key modulator of the plasminogen/plasminase system and has been demonstrated to promote tumor progression and metastasis in various tumours." (PMID 39086142, 2024). "An important translational element presented here is that pharmacological reduction of plasminogen using ASOs resulted in reduction in the growth and lung metastasis of low‐passage patient‐derived PDAC tumor cell lines in immune‐deficient mice." (PMID 37971174, 2024). "Collectively, these findings suggest that linking plasminogen to the tumor cell surface through multiple means can promote primary growth but that specific tumor cell receptor–plasmin(ogen) interactions are required to promote metastasis." (PMID 37971174, 2024). "Elimination of plasminogen significantly reduced the metastatic potential of KPC PDAC tumor cells and reduced metastasis of orthotopic Pa03C tumors." (PMID 37971174, 2024). "Collectively, these findings are similar to those observed in the KPC tumor model and suggest that plasminogen activation in the TME enhances both tumor growth and metastasis, especially metastatic burden in the lung." (PMID 37971174, 2024). "We demonstrate the efficacy of suppressing plasminogen in circulation and its effect on reducing tumor progression and metastatic burden." (PMID 37971174, 2024). "Angiostatin, the initial Kringle domain among four domains found in a 38 kDa internal proteolytic fragment of plasminogen, has been acknowledged as a potent endogenous inhibitor of angiogenesis and extensively demonstrated for its anti-tumor efficacy." (PMID 39091624, 2024). "The activation of plasminogen and extracellular matrix degradation mediated by PLAUR are important causes of tumor metastasis." (PMID 37153595, 2023).
tumor (continued). "MMP-9 helps in the degradation of plasminogen to produce angiostatin, which increases apoptosis in tumor cells." (PMID 37569509, 2023). "The COX-2 inhibitor or EP2 receptor antagonist repressed angiogenesis and tumor invasion via the uPA system, which is a determinant factor in transforming the zymogen plasminogen into plasmin for degrading the ECM constituents." (PMID 36765694, 2023). "Depletion of S100A10 in pancreatic cancer cell lines resulted in decreased cell surface plasminogen activation and an overall reduction in cell invasiveness and tumor growth." (PMID 37892132, 2023). "Plasminogen (PLG) acted as an important role in inhibiting tumor progression due to its ability to inhibit angiogenesis." (PMID 37601683, 2023). "MMP-2 and MMP-9, in particular, aid in the digestion of plasminogen and the release of angiostatin, which increases tumor cell apoptosis, and MMP-9 also breaks down collagen XVIII to produce endostatin, which inhibits angiogenesis." (PMID 37823051, 2023). "Plasminogen activator urokinase converts plasminogen to plasmin promoting the degradation of the basement membrane and facilitating tumor invasion and metastasis." (PMID 38031074, 2023). "Plasminogen-plasmin system is involved in many critical physiological and pathologic processes including cell migration, autoimmune, tumor formation and neurodegeneration." (PMID 36585464, 2022). "PLG protein expression was significantly decreased in lung metastatic and tumor tissues of anti‐Chi3L1 antibody‐treated mice." (PMID 34861103, 2022). "Tumor cells increase the production of plasminogen, activate the serine protease plasminogen activator, and induce the conversion of plasminogen to plasmin." (PMID 35371322, 2022). "Their gene ontology (GO) analysis showed the over-representation of blood coagulation and plasminogen activating cascade pathways, possibly compatible with Blood Brain Barrier damage in tumor disease and surgery bleeding." (PMID 35216175, 2022). "In this context, astrocytes represent a first defense against tumor invasions as the source of a plasminogen activator that catalyzes neuron-derived plasminogen in plasmin, which in turn induces the release of FasL from astrocytes." (PMID 36428520, 2022). "Tetraspanin can induce the activation of plasminogen to hydrolyze proteins extracellularly, and plasminogen is involved in tumor metastasis and invasion." (PMID 35936688, 2022). "Increased tumor cell motility and de-adhesion (thus, promoting metastasis), as well as upregulated plasminogen-signaling, are shown when functionally analyzing the DAPK1 ko-related proteome." (PMID 35625969, 2022). "For example, matrikines, such as endostatin a proteolytic product from type XVIII collagen, or those derived from elastin or plasminogen (angiostatin) cleavage, are anti-angiogenic and can act in a tumor-promoting or suppressing manner." (PMID 35558554, 2022). "Four genes (IFNA1, IFNG, LEP, and PLG) were excluded from analysis because their PCR Ct values were greater than 32 for both tumor and control samples, indicating that the expression of these genes was extremely low and not reliable for comparison analysis." (PMID 35600354, 2022). "Anti‐Chi3L1 antibody treatment reduces M2 polarization with STAT6‐dependent PLG signaling, eventually reducing tumor growth and cancer metastasis." (PMID 34861103, 2022). "The same research group subsequently found that CBD downregulates the expression of PAI-1, a plasminogen system inhibitor that promotes tumor growth, angiogenesis, and invasiveness." (PMID 36437760, 2022). "Recent studies demonstrate that tumor tissues of various organs lay down specific matrisomes (ECM and ECM-associated proteins), including fibrinogen or plasminogen." (PMID 33669052, 2021). "PLG has broad substrate specificity, which not only supports the migration and invasion of tumor cells due to the enzymatic properties of fibrinolytic enzyme but also has antiangiogenesis and antitumor factors." (PMID 33968297, 2021).
tumor (continued). "On the other hand, dysregulation of the plasminogen/plasmin system is also involved in tumor growth and metastasis formation." (PMID 34082810, 2021). "In this review, we provide a detailed discussion of the roles of plasminogen activation system in tumor growth, invasion, metastasis, and chemoresistance with specific emphasis on their role in the TME." (PMID 33921488, 2021). "Similar to TAMs, astrocytes can cooperate with tumor cells in remodeling the ECM via a mechanism involving plasminogen activation." (PMID 34690699, 2021). "PGK1 is secreted extracellularly by different types of tumors, acting as a disulfide reductase that serves to cleave plasminogen, thereby generating the tumor blood vessel inhibitor angiostatin." (PMID 33363463, 2020). "This protein is a heparin-binding, cell adhesion modulator that have capability to alter tumor cell invasion and metastasis by modulating tumor cell adhesion and the plasminogen/plasminogen-activator system." (PMID 31983196, 2020). "Angiostatin, a plasminogen fragment characterized with antiangiogenic effects, was able to suppress metastasis growth in vivo by inhibiting tumor angiogenesis." (PMID 31552179, 2019). "It has been indeed demonstrated that ANG interacts with the plasminogen activation system, thus increasing plasmin formation and cell migration of tumour cells." (PMID 31500197, 2019). "Cell surface enolase links with TEM8, together with uPA and plasminogen, to form a highly efficient proteolytic cascade at the tumor cell surface, which promotes tumor metastasis." (PMID 30241478, 2018). "S100A10 specifically binds to plasminogen, and plasminogen activation is a key step in tumor growth and invasion." (PMID 29324674, 2018). "Among these proteases, the Plasminogen activators (PA)/plasminogen system controls proteolysis thus, facilitating tumour invasiveness and growth." (PMID 30112117, 2018). "The enolase/plasminogen system is one of the mechanisms facilitating the invasiveness of pathogens, and it plays also an important role in the development of tumor tissues." (PMID 28696348, 2017). "Local vascular permeability with consequent extravasation of fibrinogen and plasminogen initiate the formation of fibrin gel deposits, the early form of tumor stroma, which attracts migrating fibroblasts, epithelial cancer cells and inflammatory cells." (PMID 28216675, 2017). "To evaluate the biological effect of plasminogen activators on tumor growth, we used tranexamic acid as a plasminogen inhibitor." (PMID 29123986, 2017). "Our results suggest that excessive tumor growth induces progalanin activation via the u‐PA/plasminogen system." (PMID 29123986, 2017). "The interactions of uPAR with Cyr61 significantly correlated with expression levels of tumor-promoting biomarkers including plasminogen (p=0.0014), cathepsin B (p=0.032), c-Met (p=0.0192) as well as with the tumor grade (p=0.02)." (PMID 27286449, 2016). "In tumor cells, the expression of Eno-1 was up-regulated and supported anaerobic proliferation (Warburg effect), driven tumor invasion through plasminogen activation and extracellular matrix degradation." (PMID 26918350, 2016). "Our investigations have generated new and valuable biological information about the cell types being involved in tumour invasive and progression through the plasminogen activation system." (PMID 26292086, 2015). "Surface actin in endothelial cells has been demonstrated to serve as a receptor for angiogenin, plasminogen and tissue plasminogen activator, proteins which play central role in angiogenesis and tumor progression." (PMID 25815360, 2015). "Activation of the plasminogen system is tightly regulated, which is necessary to prevent the development of a systemic fibrinolytic state or tumor metastasis." (PMID 26054637, 2015).
tumor (continued). "As highlighted by others, our investigations have generated new biological information about the cell types being involved in tumour invasion and progression through the plasminogen activation system." (PMID 26292086, 2015). "Our investigations have generated new and valuable biological information about the cell types being involved in tumour invasion and progression through the plasminogen activation system." (PMID 26292086, 2015). "Previous studies of the plasminogen-plasmin system in cancer suggested the importance of this system in facilitating tumor cell invasion by uPA-mediated activation of plasmin and subsequent degradation of extracellular matrix." (PMID 26164207, 2015). "The uPA gene encodes a serine protease involved in the degradation of the extracellular matrix and possibly tumor cell migration and proliferation by regulating the plasminogen/plasmin system." (PMID 26033187, 2015). "Activation of the fibrinolytic plasminogen/plasmin system results in degradation of protein barriers, thereby mediating cell migration essential for tumor growth, angiogenesis, and dissemination." (PMID 26740968, 2015). "DDAVP seems to modulate tumour angiogenesis by inducing the formation of angiostatin, a potent angiogenesis inhibitor that is generated by cancer-mediated proteolysis of plasminogen." (PMID 25846632, 2015). "Urokinase-type plasminogen activator (uPA) is a 55-kDa serine protease that activates plasminogen to plasmin leading to cell matrix degradation, which is involved in tumor cell adhesion, migration, invasion and intravasation." (PMID 25176506, 2014). "Activation of plasminogen to plasmin in the tumor microenvironment leads to a cascade of proteolytic activities in addition to malignant cell migration and angiogenesis, thus enhancing invasion and dissemination." (PMID 24889870, 2014). "Mainly, the tumor suppressor role of these MMPs is related to their ability to degrade plasminogen, collagen XVIII, and collagen IV to produce natural angiogenic inhibitors, such as angiostatin, endostatin, and tumstatin." (PMID 24578639, 2014). "It is generated through proteolytic cleavage of circulating plasminogen by a series of enzymes from the tumor environment, including the MMPssuch as MMP-2, MMP-7, MMP-9, and MMP-12." (PMID 25549350, 2014). "Angiostatin, an internal fragment of plasminogen inhibits EC proliferation and metastatic tumor cell growth." (PMID 25549350, 2014). "This indicates that plasminogen activation with all the successive effects is an inherent property of the tumor from the beginning of malignant growth until the end stage." (PMID 24889870, 2014). "In the MMTV-PymT model of mammary gland carcinogenesis, PLG deficiency markedly reduced the number of spontaneous pulmonary metastases pointing towards the in vivo role of PLG in tumor spread." (PMID 25407528, 2014). "They suggested that ANXA2 at the cell surface of tumor/endothelial cells provides for the mechanical assembly of plasminogen activator and plasminogen, which locally activates plasminogen to plasmin." (PMID 23950866, 2013). "In particular, components of the plasminogen system participate in tumor growth, invasion and metastasis." (PMID 23594883, 2013). "Plasminogen activation has been found to be positively correlated with tumor malignancy, and, in accordance, increased serum levels of uPA and uPAR have been positively correlated with poor prognosis in patients with prostate and breast cancer." (PMID 23894455, 2013). "The protease u-PA converts plasminogen to plasmin, which is capable of promoting tumor growth and angiogenesis, degrading the ECM and basement membrane and activating pro-MMPs." (PMID 23563849, 2013). "The serine protease u-PA converts plasminogen to plasmin, which is capable of promoting tumor growth and angiogenesis, degrading the ECM and basement membrane and activating pro-MMPs." (PMID 23661254, 2013).
tumor (continued). "In this model, tumor cell invasion is mainly due to cell adhesion to Matrigel® and to the proteolytic degradation of Matrigel® by MMPs and the plasminogen activation system." (PMID 22539938, 2012). "It is worth noting that tumour metastasis correlates with plasminogen activity due to the degradation of the extracellular matrix by the plasminogen product, plasmin." (PMID 22363418, 2012). "It has been reported that a protective role of stromal cell-derived MMP-12 in lung metastatic tumour growth is due to inhibition of angiogenesis by angiostatin formation from plasminogen by MMP-12." (PMID 22015555, 2011). "Plasminogen is cleaved by several proteases, among them members of matrix metalloproteinase family, that are derived from tumor cells or infiltrating macrophages." (PMID 21787393, 2011). "To analyse the effects of EDPs on PAs uPA and tPA, we performed gelatin plasminogen zymography from tumour lysates and conditioned culture media." (PMID 20959825, 2010). "For several decades, it has been postulated that plasminogen activation plays an important role in tumor invasion and metastasis." (PMID 20957082, 2010). "We suggest that exosome contents are released outside the tumor cell in close proximity to each other and other inactive extracellular pro-invasive proteins such as plasminogen." (PMID 20553606, 2010). "Angiostatin is a large peptide fragment of plasminogen endowed with anti-angiogenic properties originally isolated from the urine of tumor-bearing mice." (PMID 19144161, 2009). "The uPAR glycoprotein, receptor of plasminogen activation system, plays a central role in extracellular matrix degradation; thus, it participates in tumour invasion and metastasis." (PMID 18522728, 2008). "A second scenario must be considered, in which K8 serves as a receptor for plasminogen and tPA at the plasma membrane of tumour cells." (PMID 18803884, 2008). "MMPs are major players of ECM proteolysis at the cell surface in tumor invasion and metastasis, exposing and activating cryptic epitopes from, e.g., laminins, enhancing cell migration or from plasminogen, inhibiting angiogenesis." (PMID 18382662, 2008). "The plasminogen activation system plays a role in cancer progression via extracellular matrix degradation and tumor cell migration." (PMID 16945123, 2006). "Plasminogen activators are known to play a key role in the remodeling of bone matrix which occurs during tumor progression, bone metastasis and bone growth." (PMID 16569238, 2006). "This suggests that sulfated GAGs liberated by tumor cells, mediate ECM degradation amplifying pericellular plasminogen activation and locally enhancing tumor cell invasion in a positive feedback." (PMID 16111491, 2005). "The plasminogen activation system plays a role in cancer progression, presumably via extracellular matrix degradation and tumour migration." (PMID 16091756, 2005). "There is substantial evidence that high concentrations of the urokinase plasminogen-activating system are conducive to tumour cell spread and metastasis." (PMID 15226768, 2004). "The plasminogen activation system, necessary for clot degradation, and also involved in wound healing and inflammation, is one of such mechanisms incorporated by tumour cells for developing the metastatic phenotype." (PMID 12556966, 2003). "To determine the effect of tumour cell-produced thrombospondin-1 in the regulation of the plasminogen/plasmin system and tumour cell invasion, we studied THBS-1 -transfected MDA-MB-435 breast cancer cells that overexpress thrombospondin-1." (PMID 10917542, 2000). "Angiostatin, a potent inhibitor of angiogenesis, tumour growth and metastasis, is a biologically active fragment of plasminogen, containing the kringle domains 1–4." (PMID 10604721, 1999). "Our results demonstrate that TNF-alpha and IL-1 beta stimulate the plasminogen activation system in tumour cell but the responses differed even in cells derived from the same tissue origin." (PMID 8826848, 1996).